CDK4 (cyclin dependent kinase 4)
Diseases named in the same sentence as CDK4 in open-access papers (continued):
Sharing a sentence is not in itself a finding about the gene and the disease.
cancer (continued). "Combined with cyclin D (CCND), CDK4 controls cancer cells from the G1 phase to S phase for DNA synthesis and expedites cell proliferation." (PMID 27708221, 2016). "Since several CDK4/CDK6 inhibitors have been also used in clinical trials in various types of cancers, it would be worth investigating the effectiveness of combinational therapies using BET bromodomain inhibitors as well as CDK6 inhibitors for SCLC patients." (PMID 27764802, 2016). "These proteins have been considered pivotal target proteins in various cancers because many anti-cancer drugs can inhibit the expression of cyclin D1 and CDK4." (PMID 27670681, 2016). "As the regulatory subunits of CDK4 or CDK6, CCND1 and CCND2 are required for cell cycle G1/S transition, and thus have been implicated as proto-oncogenes and attractive targets for cancer therapy." (PMID 27494902, 2016). "To date, the RB1 pathway in human cancers has been reported to be disrupted only by loss of expression of CDKN2A or RB1, as well as by CDK4/CCND1 over- expression, even though SWI/SNF is known to be an essential cofactor for RB1 function." (PMID 28105458, 2016). "The frequency of CDK4/CDK6 deregulations observed in transformed cells suggests that many cancer cells are dependent on high CDK4/CDK6 activity." (PMID 27323399, 2016). "It has been reported that the cell cycle regulatory protein expression of cyclin A, cyclin E, cyclin D, Cdk4, Cdk6 and Cdk2 were inhibited by the activation of p21 in human cancer cells." (PMID 27007366, 2016). "The CDK4 gene is frequently amplified in human cancer and its deregulation has been observed in many types of human cancers." (PMID 27759034, 2016). "The recent development of selective CDK4 inhibitors launched the first successful efforts to target the CDK4 pathway for cancer therapy." (PMID 26528855, 2015). "Most human cancers contain overactive CDK4/6-cyclin D, and CDK4/6-specific inhibitors are promising anti-cancer therapeutics." (PMID 25562820, 2015). "Amplification or deletion of genes involved in the RB signalling pathway were seen in 60% (18 of 30) of metastases, which is of interest given the significant activity of CDK4 inhibitors in other cancers." (PMID 25886454, 2015). "Cell cycle deregulation is crucial for various oncogenic transformation processes, suggesting that many cancer cells depend on high CDK4/6 activity." (PMID 26528855, 2015). "The CDKs and cyclins that are most frequently affected by somatic nucleotide alterations in various cancers are CDK4 and cyclinD1." (PMID 26252490, 2015). "In cancer cells that have overactive CDK4/6-cyclin D1 activity and a functional Rb protein, CDK4/6 inhibitors block Rb phosphorylation, preventing its deactivation, and leading to G1 cell-cycle arrest or senescence." (PMID 26337082, 2015). "This docking analysis gives a “theoretical quantitative” assessment of the binding efficiencies of CDK4 native and mutant proteins with the cancer drug flavopiridol." (PMID 26252490, 2015). "The CDK4-cyclin D1-p16 retinoblastoma protein (RB1) pathway (CDK4 pathway) promotes the G1-S cell cycle transition and is commonly dysregulated in most cancers." (PMID 26252490, 2015). "The critical well-known function of P21 is to block cell proliferation in normal and cancer cells by inhibiting the activity of kinases important for G1/S transition such as CyclinD/CDK4, CyclinD/CDK6 and CyclinE/CDK2." (PMID 26384350, 2015). "Taking these data together suggests that functional inactivation of CDK4/6 is an important mechanism for cellular senescence induction in various cancers." (PMID 25684390, 2015).
cancer (continued). "The growth of cancer cells in vitro is inhibited by BPT at much lower concentrations than it inhibits the enzyme Cdk4-cyclin D1 in vitro." (PMID 25950473, 2015). "Deregulation of the G1 checkpoint is crucial for various oncogenic transformation processes, suggesting that many cancer cell types depend on CDK4/6 activity." (PMID 26528855, 2015). "Our results indicate that the level of APC/CFZR1 activity is an important contributing factor in response of cancer cells to CDK4/6 inhibitor treatment." (PMID 25562820, 2015). "They show specificity towards Cdk4-cyclin D1 enzyme activity and blocks the growth of cancer cells at the G0/G1 phase." (PMID 25950473, 2015). "Together, our data indicate that not only the mutant or WT status of Rb but also the expression levels of FZR1 and functional activity of the APC/CFZR1 E3 ligase will determine how cancer cells respond to CDK4/6 inhibitor treatment." (PMID 25562820, 2015). "Overall, this computational investigation of the CDK4 gene highlights the link between genetic variation and biological phenomena in human cancer and aids in the discovery of molecularly targeted therapies for personalized treatment." (PMID 26252490, 2015). "Given the modest response to CDK4/6 inhibitors we interrogated the impact of PD-0332991 on 304 anti-cancer compounds." (PMID 25156567, 2014). "PD 0332991, a CDK4/6 inhibitor, was used in a Phase I clinical trial in patients with advanced cancer." (PMID 25349887, 2014). "Previous studies suggested that the overexpression of cell cycle-related proteins, such as D1 and Cdk4, is correlated with the proliferation of human cancer cells." (PMID 24960186, 2014). "These recent results support the clinical potential for selective targeting of CDK4/6 in the treatment of cancer." (PMID 24919854, 2014). "The importance of the pathway in tumorigenesis and recent success developing small molecule kinase inhibitors, make CDK4/6 a highly validated cancer drug target." (PMID 24919854, 2014). "The development of small molecule inhibitors targeting the cyclin-CDK4/6-RB axis for cancer therapy is crucial." (PMID 24765199, 2014). "The CDK4 protein regulates and promotes cell cycle progression through G1, and elevated levels are common in cancer." (PMID 24835790, 2014). "Preclinical and clinical studies have demonstrated the anticancer activity of PD-0332991, a selective cyclin-dependent kinase 4/6 (CDK4/6) inhibitor, in the treatment of various types of cancer in a retinoblastoma protein (RB)-dependent manner." (PMID 24765199, 2014). "dFMGEN, a novel genistein derivative, is a candidate for cancer therapy, arresting the cell cycle at G1 phase with significant reduction of CDK4 and CCND1 protein levels." (PMID 24605326, 2014). "Transition through the restriction point requires phosphorylation of retinoblastoma protein (Rb) by CDK4/6, which are highly validated cancer drug targets." (PMID 24919854, 2014). "To examine the effects of CDK4/6 knockdown and RB phosphorylation inhibition on cancer cell growth, we transduced the shRNA-coded vectors in COLO320 cells, selected stably transduced cells and examined cell growth using a cell viability assay." (PMID 24765199, 2014). "In “pathways in cancer”, both the transcriptomic results and qPCR data revealed that 7 DEGs, including cdk4/6, ptenl, fu, cdk2, ral, faks, and elongb, are all upregulated by Ras1CA, while fakl is downregulated." (PMID 24606580, 2014). "In other types of cancer such as the ovarian, urinary bladder, endometrial or oral, CDK4 expression is impaired." (PMID 25349887, 2014).
cancer (continued). "The corollary of the central position of T172-phosphorylation of CDK4 in the cell cycle decision module is its responsiveness to various drugs or treatments used or envisaged in cancer therapy." (PMID 23737759, 2013). "An unchecked or hyperactivated Cyclin D1/CDK4 complex often leads to uncontrolled cell division and therefore cancers." (PMID 23800091, 2013). "Such deregulation is crucial for various oncogenic transformation processes suggesting that many cancer cells are addicted to high CDK4/6 activity." (PMID 23737759, 2013). "PD-0332991 is one of several CDK4/6 inhibitors currently in clinical development for the treatment of cancer." (PMID 24098593, 2013). "Overall, the ability of CDK2 and CDK4 to mediate various malignant phenotypes that play important roles in cancer biogenesis has prompted the development of CDK2 or CDK4 specific inhibitors." (PMID 23886499, 2013). "All three types of cancer display distinct genomic aberration patterns in 12q14-15 region in spite of having MDM2/CDK4 co-amplification." (PMID 24261984, 2013). "Some compounds derived from natural sources have been shown to inhibit the cell cycle at points regulated by various components of the Cdk4 pathway, blocking proliferation of cancer cells." (PMID 23530816, 2013). "They thus play a central role in the cell multiplication decision, especially in most cancer cells in which CDK4 activity is highly deregulated." (PMID 23737759, 2013). "In this work, FoxM1 was also identified as a critical substrate of CDK4/6 kinases that mediates senescence suppression in cancer cells through ROS regulation and the activation of genes required for the G1/S transcription." (PMID 23467617, 2013). "This provides an excellent therapeutic window for targeting Cdk4/6-FoxM1 signaling in order to reactivate a senescence program in cancer cells." (PMID 23467617, 2013). "Since overexpression of Kv1.3 channels is known to affect the cell cycle progression in various types of cancer cells, we then examined the expression of cell cycle markers, such as cyclin-dependent kinase 4 (Cdk4) and its inhibitor, p21." (PMID 22701172, 2012). "The paradigm relating cell cycle control, cyclin-dependent kinases and cancer has changed from our classical understanding, however, with reappraisal of the mandatory requirement of Cdk2, Cdk4 or Cdk6 for normal cell division." (PMID 21668989, 2011). "Cdk1 and Cdk4 have been shown to have closely correlated expression across a wide range of human cancer cell lines." (PMID 21668989, 2011). "A high incidence of mutations in Rb, along with cyclin D and p16(INK4a), has been seen in tumorigenesis in many cancers, a fact which has recently seen CDK-4 become an exciting new cancer drug target." (PMID 22073013, 2011). "The cyclin-D/CDK4,6/p16INK4a/pRB/E2F pathway, a key regulator of the critical G1 to S phase transition of the cell cycle, is universally disrupted in human cancer." (PMID 21799732, 2011). "CDK4 has gained prominence as a significant cancer-related gene, as its function is to drive cell-cycle progression by phosphorylating the retinoblastoma protein." (PMID 21477379, 2011). "For subtypes 7.2 and 7.3, several CDK4 inhibitors are currently in development for a variety of cancer types." (PMID 21479172, 2011). "It is well known that p16INK4α plays an essential role in the development of most human cancers for the reason that the p16/cyclinD1/CDK4/RB signaling pathway controls the cell cycle at the G1/S transition." (PMID 22174919, 2011).
cancer (continued). "Alterations in the proteins that regulate the early stages of the cell cycle, including Cdk4, D-type cyclins and E2f1, have proven to be important in the development of cancer." (PMID 20090907, 2010). "Inhibition of this pathway by using, for example, selective Cdk4 inhibitors has been suggested to be a promising approach for cancer therapy." (PMID 19551155, 2009). "In fact, in our study, obese patients (BMI ≥ 30) with CDK4 IVS4-nt40AA genotype have a significant increased risk for cancer and tumors/cancer, in both datasets tested." (PMID 19327170, 2009). "Although ID-1 has been shown to interact with various cell cycle regulators, ID-1 seems to be an essential factor in the promotion of G1/S cell cycle transition in certain cancers by inactivating of p16 and increasing of CDK4 activity/RB." (PMID 19002177, 2008). "Recently it was demonstrated that p16ink4a was present in protein complexes and bind with Cdk4/6 in both cytoplasmic and nuclear fractions of several cancer cell lines." (PMID 17359536, 2007). "CDK4 activity is crucial in various tumorigenesis models and appears as a very attractive target for cancer therapy." (PMID 17092340, 2006). "The so widespread deregulation of CDK4 in cancers underscores the necessity to fully understand the various mechanisms involved in its activation process." (PMID 17092340, 2006). "In agreement with the gene expression profile of CDK4, its cytoplasmic staining was increasing from 20% in normal urothelial cells to 100% of cancer cells." (PMID 16265353, 2005). "The nucleic CDK4 staining was also increasing from 5% in normal urothelial cells to 50% in cancer cells." (PMID 16265353, 2005). "In addition to breast cancer, there are some ongoing and completed clinical trials applying CDK4/6 inhibitors to other cancers." (PMID 41584037, 2026). "RB1 co-deletion with BRCA2, due to synteny on chromosome 13q, may explain reduced efficacy of CDK4/6 inhibitors in BRCA2 mutant cancers." (PMID 41512445, 2026). "In sum, our study uncovers a novel cell cycle control mechanism by ZDHHC17-mediated palmitoylation and TRAF6-mediated ubiquitination of CDK4, presenting a potential therapeutic avenue by targeting the ZDHHC17-TRAF6-CDK4 axis for cell cycle dysregulated cancers." (PMID 42133178, 2026). "Deregulation of the CDK4/6-cyclin D-INK-RB pathway has been found in a variety of cancers." (PMID 41584037, 2026). "Oncogenes such as MYC, AKT1, AKT2, cyclins CCNA2, CCNB1, CCNB2, CCNE1, CCNE2 and cyclin-dependent kinases CDK1 and CDK4, which were upregulated under androgen treatment, exhibited a significantly reduced expression following PVT1 knockdown, thereby modulating cancer-associated oncogenic pathways." (PMID 41792045, 2026). "However, the emergence of resistance to CDK4/6 inhibitors in malignant tumors poses a challenge to their therapeutic efficacy and clinical application." (PMID 39852139, 2025). "However, the efficacy for CDK4/6 inhibitors varies in different types of cancer and thus there is a need to identify new biomarkers that would help predict efficacy and/or resistance." (PMID 41154395, 2025). "The D- CDK4/6 regulates the G1-S phase transition, which is often dysregulated in cancer." (PMID 40723282, 2025). "CDK4 is a well-known cancer target that regulates cell cycle and proliferation." (PMID 40075679, 2025). "Among all the CDK/cyclin complexes, aberrations resulting in hyperactivity of the CDK4/cyclin D complex are observed in numerous human cancers, with the most prevalent being breast carcinoma, melanoma, osteosarcoma, liposarcoma, glioblastoma, and neuroblastoma." (PMID 41375037, 2025).
cancer (continued). "Hence, palbociclib, a selective CDK4/6 inhibitor, for CDK4/6-driven RB1 defects is also a promising option for RBNSig-BC–identified aggressive cancers." (PMID 40138429, 2025). "As previously observed in immune cells, CDK4/6 inhibitors may induce the upregulation of several costimulatory surface molecules in cancer cells." (PMID 41388212, 2025). "Furthermore, sensitive cancers invariably acquire resistance to CDK4/6 inhibition, such that CDK4/6i’s are only efficacious in combination with drugs that target other pathways on which cancer cells rely to escape CDK4/6 dependency." (PMID 40696167, 2025). "However, both pre-clinical studies and clinical trials imply that the deregulation of CDK4/6/Cyclin D/RB node has variable repercussions dependent on the genomic micro-environment of a given cancer." (PMID 40699853, 2025). "Third, rebound in cancer cell proliferation after cessation of a CDK4/6 inhibitor is recognized, and the prognostic relevance of the rebound is unknown." (PMID 40888443, 2025). "From January 2017 to October 2020, 456 patients who were diagnosed with hormone receptor‐positive, HER2‐negative ABC and treated with a CDK4/6i in combination with an aromatase inhibitor at the Yonsei Cancer Center were enrolled in this study (CONSORT diagram)." (PMID 39686815, 2025). "Further preclinical and clinical researches are necessary to understand if CDK4/6 inhibitors could be successfully used also in other cancer types of cancer and/or other human diseases." (PMID 39800748, 2025). "As preclinical studies and clinical trials advance, the use of CDK4/6 inhibitors—particularly in combination regimens—is anticipated to become increasingly widespread, potentially extending therapeutic benefits to a growing number of cancer patients." (PMID 40563591, 2025). "The innate resistance of these cancers to CDK4/6 inhibitor monotherapy may relate to the over-expression of cyclin E, which could continue driving the cell cycle in the presence of CDK4/6 inhibition." (PMID 40699853, 2025). "Cancer cells can develop resistance to CDK4/6 inhibitors through various mechanisms, including adaptive alterations in cell cycle regulatory pathways, reactive activation of bypass signalling pathways, and interactions with cancer-related immune cells in the microenvironment." (PMID 40563591, 2025). "Accumulating evidence indicates that CDK4/6 inhibitors may influence cancer cell proliferation and survival by either affecting key metabolic pathways or triggering metabolic reprogramming." (PMID 41388212, 2025). "Concurrently, recent studies have revealed the unexpected effects of CDK4/6 inhibitors on cancer cell senescence, metabolic state, and immune status, which may contribute to drug resistance and may guide future cancer therapeutics." (PMID 40563591, 2025). "Explaining these differences at the conformational level could clarify the shifts towards the CDK6 complex for cell cycle progression in resistant cancer cells, thereby bypassing CDK4/6 inhibition." (PMID 40093074, 2025). "Furthermore, the presence of the pathogen inhibited the expression of cyclin D1 and CDK4 in cancer cells, and increased CDK inhibitor p21CIP1/WAF1 level compared to uninfected control cells." (PMID 41228271, 2025). "This redundancy in the control of RB phosphorylation suggests that the effectiveness of CDK4/6is may be improved in some cancers by combining CDK2 inhibition with CDK4/6is." (PMID 40282469, 2025). "Overall, the data from this analysis provided further support for the favorable immune-modulatory role for CDK4/6 inhibitors, which could be exploited to boost the efficacy of ICIs and improve response rates in cancer patients." (PMID 40856900, 2025). "In contrast, the expression levels of miR-122-5p diminish, implying that the overexpression of CDC25A and CDK4 may enhance the viability of these cancer cells and suppress apoptosis." (PMID 41373559, 2025).